CD34 (CD34 molecule)
Diseases named in the same sentence as CD34 in open-access papers (continued):
Sharing a sentence is not in itself a finding about the gene and the disease.
infection (continued). "To investigate the dynamics of Mtb infection by HSPCs, we have exposed peripheral blood mononuclear cells (PBMCs) from healthy donors to H37Rv Mtb (multiplicity of infection, MOI3) and measured bacterial infectivity by CD34+ cells." (PMID 31637998, 2019). "CMV infection blunts EGFR signaling and downstream pathways in productive infection, but EGFR signaling and that of downstream pathways is sustained in CD34+ HPCs." (PMID 31725811, 2019). "As expected, treatment of experimentally latently infected CD14+ monocytes and CD34+ progenitor cells with F49A-FTP led to a reduction in latently infected cells, as measured by decreases in GFP-expressing latent cells after infection with a GFP-tagged HCMV50." (PMID 28148951, 2017). "As shown, possibly in response to HCMV early infection, the levels of IER5 in the Kasumi-3 cells and CD34+ HPCs infected with NR-1 or NR-1ΔmiR-UL148D were increased during the early days (1–4 dpi) of infection." (PMID 27824944, 2016). "In contrast to infection in fibroblasts, EGFR surface levels were increased 1 dpi in WT-infected CD34+ HPCs relative to uninfected CD34+ HPCs." (PMID 27218650, 2016). "At 48 hours post-infection with GFP-expressing NR-1 at a multiplicity of 2 PFU/cell, GFP expression was detected in 13.2% of the Kasumi-3 cells and 12.3% of the CD34+ HPCs." (PMID 27824944, 2016). "In humanized mice transplanted with either CD4+ T cells or CD34+ HSC, ZFN-mediated CCR5 disruption has been shown to confer resistance to de novo infection by CCR5-tropic HIV-1, thereby controlling virus replication." (PMID 24086129, 2013). "To establish an HIV-1-infected humanized mouse model, we infected hNOK/B51Tg and hNOK mice at 14 weeks after the transplantation of CD34+ HSCs with HIV-1NL4-3 and analyzed their plasma viral load every 2 weeks post-infection." (PMID 22880104, 2012). "Inoculating ex vivo HTLV-1 infected CD34+ HP/HSC in immunodeficient mice is confusing the humanization process with the infection procedure, which is quite different of the natural infection conditions." (PMID 22969759, 2012). "We showed that the decreased engraftment potential of the LSK population on day 8 post-infection correlated with a decrease in the number of dormant HSCs, where dormant HSCs were characterized as LSK CD150+ CD48− CD135− CD34− cells." (PMID 22194881, 2011). "During E. muris infection, the frequency and number of LSK CD34− CD135− cells increased, suggesting that infection promotes the proliferation of true HSCs." (PMID 22194881, 2011). "On day 8 post-infection the number of LSK CD150+ CD48− CD34+ CD135− cells was decreased, but the more differentiated LSK CD150+ CD48+ CD34+ CD135− and LSK CD150− CD48+ CD34+ CD135− cells increased in number." (PMID 22194881, 2011). "At ten days post-infection (p.i.), RNA from JUNV-inoculated CD34+ cells displayed a fragment of the viral genome, while RNA from cultures exposed to the UV-irradiated JUNV strain did not." (PMID 20419155, 2010). "Again, trans-infection was abrogated by the selective incapacitation of surface-bound HIV-1 virions in both MDDCs and CD34-derived LCs." (PMID 18584030, 2008). "EGFP expression was observed in the CD34+ population in the TN9-8GF5 amplicon (0.3%, 0.1%) (&7b) or the CMV-EGFP virus (0.6%) at 36 hours post infection." (PMID 15673469, 2005). "(D) Schematic of infection of WT and Il27–/– mice for E and F. (E) Numbers of LTHSCs and granulocyte progenitors (GPs) (CD3−, NK1.1−, B220−, CD117+, CD34+, CD16/32hi, Ly6C+, CD135−, CD115−) in the bone marrow of WT and Il27–/– infected mice throughout infection." (PMID 41396163, 2025). "Therefore, the GFP+ cells (hereafter referred to as HCMVGFP+) following RV-TB40-BACKL7-SE-EGFP infection represent productively infected cells, while the GFP− cells (hereafter referred to as HCMVGFP−) are enriched for ‘truly’ latently infected CD34+ cells." (PMID 40872823, 2025). "After primary infection, HCMV can establish latency in bone-marrow-resident CD34+ progenitor cells." (PMID 39452693, 2024).
infection (continued). "Finally, in the Hu-SGM3 (CD34+) model, six cytokines were detected, including IFN-α (2/3 mouse) and IFN-γ (3/3 mouse) by day 21 post-infection." (PMID 39204240, 2024). "The limited infection rate does not necessarily preclude CD34+ progenitor cell or B cell-mediated entry, as a virus attached to or within B cells is sufficient to infect glial cells in the culture." (PMID 37896889, 2023). "Finally, treatment of infected animals with G-CSF induced the reactivation of infection, which was confirmed by PCR in human CD14+, CD169+, and CD34+ cells in the different tissues and by in vivo imaging." (PMID 37513800, 2023). "Overall, the results suggest that DENV does not impair the function of CD133 and CD34, is not killed due to infection, and accounts for the permissive subsets of DENV infection." (PMID 37386042, 2023). "Infection of CD34+ cells only had a non-significant tendency to correlate with the number of CD34+ cells studied, age of the patient, time since diagnosis, and viral load." (PMID 36230931, 2022). "This led to a graft engineering approach that selectively depleted CD45RA naïve T cells, preserving the CD34+ fraction critical for engraftment and CD45RO memory cells that could maintain T cell activity against infections and tumors." (PMID 36505500, 2022). "The mechanisms used by HCMV to regulate proapoptotic cellular proteins upon infection of CD34+ HPCs have not been fully explored." (PMID 33408225, 2021). "In addition, PDGFR is not reported to be expressed on freshly-isolated blood monocytes or freshly-isolated CD34+ HPCs suggesting that the gB/EGFR interaction plays a key role in the infection of these cell types." (PMID 34025614, 2021). "CD34+ hematopoietic progenitor cells infected with an HCMV recombinant lacking exon 4 (and therefore lacking IE19 and the CTD) were found to harbor less viral DNA 35 days after infection than WT virus-infected cells." (PMID 32994332, 2020). "Viruses that lacked UL136p23/UL136p19 replicated but failed to establish latency in CD34+ HPCs as shown by a high frequency of infectious centers pre-reactivation compared to wild-type infection." (PMID 32630219, 2020). "Furthermore, CCR5 and CXCR4, the receptors for HIV infection, are expressed at the surface CD34+CD133+ HSPCs from umbilical cord blood and that CXCR4 was necessary for the infection by HIV-1." (PMID 33102251, 2020). "HCMV transcriptionally downregulates EGFR during lytic infection and targets EGFR for turnover but utilizes the receptor during entry into monocytes and CD34+ HPCs, where EGFR signaling is critical for trafficking of the viral genome to the nucleus (31, –, 34)." (PMID 32759334, 2020). "When sorted purified cord-blood CD34+ cells were exposed to Mtb H37Rv (MOI3) and cultivated in StemSpan SFEM II, bacilli numbers exhibited a ~ 1.5 log growth at 5 days post infection (dpi)." (PMID 31637998, 2019). "CD34+ hematopoietic stem cells (HSC) and derived monocytes, macrophages, and dendritic cells are important sites of CMV latency and reactivation, as well as of lytic infection in vivo." (PMID 30949159, 2019). "Secondly, MCL-1-mediated protection from apoptosis is a relatively transient event in CD34+ cells, with latently infected CD34+ cells no longer protected from cisplatin A-induced apoptosis 12 h post-infection." (PMID 29547547, 2018). "The result of this activity serves to reprogram these CD34+ HPCs into a subset of immunosuppressive monocytes, which fails to occur following infection with a US28-deletion virus." (PMID 30127279, 2018). "Hematopoietic cells such as CD34+ human progenitor cells (HPCs) and their more differentiated counterparts—monocytes—do not support a true replicative infection (at least not initially)." (PMID 30274264, 2018). "Neutrophils have also been implicated in hematogenous dissemination of HCMV, and like monocytes and CD34+ HPCs, do not support a productive (replicative) infection." (PMID 30274264, 2018).
infection (continued). "The associated correlation (Spearman coefficient of 0.67) is likely heavily driven by high expression of lncRNAs in both contexts, despite the fact that a large number of genes are expressed in a “lytic” infection but not in CD34+ HPCs." (PMID 29895640, 2018). "Infection of YFP+CD34+ SCC cells with the rescue construct, but not the empty vector, efficiently restored Tgfbr2 mRNA expression." (PMID 28219480, 2017). "In order to define the correlation of the VP1u receptor expression with the cellular permissivity for B19V infection, we expanded CD34+ hematopoietic stem cells ex vivo towards the erythroid lineage and tested the MS2-VP1u internalization, virus uptake and infection along the differentiation." (PMID 27690083, 2016). "In contrast, possibly due to the lack of miR-UL148D, both the Kasumi-3 cells and the CD34+ HPCs that were infected with NR-1ΔmiR-UL148D failed to suppress IER5 expression at later stages of infection, leading to sustained inhibition of CDC25B." (PMID 27824944, 2016). "We found that viral genomes increased significantly through 4 days post-infection (dpi) and then reached a plateau, whereas viral IE1 transcripts peaked at 4 dpi and then decreased to undetectable levels by 10 dpi in both Kasumi-3 cells and CD34+ HPCs." (PMID 27824944, 2016). "Adult human marrow-derived CD34+ cells and control permissive 293T cells were exposed to pseudotyped virus at a MOI of 10, with and without cytokines, and DNA was extracted at various times post-infection and analyzed by PCR as before." (PMID 26945863, 2016). "We therefore chose to compare some aspects of our data to a published large-scale study of human CD34+ cells obtained after in vitro infection with a non-replicating MLV vector." (PMID 24586197, 2014). "RNA-Seq showed that infected CD34 (+) cells did not undergo the same robust HCMV viral gene expression pattern as observed with initial infection of CD14 (+) monocytes." (PMID 23717203, 2013). "At 10 days post infection of CD34 (+) cells, no IE2 mRNA was detected, however transcripts for UL44, UL84 and the two lncRNAs were detected." (PMID 23717203, 2013). "At 24 hours post-infection (p.i.), viral antigen (NP) was expressed in CD34+ HSCs when infected with live H5N1 virus but not heat-killed virus." (PMID 24339969, 2013). "For CD34 (+) cells, we evaluated mRNA expression at 3 days post infection as well as at a time point when IE2 transcripts were no longer detected." (PMID 23717203, 2013). "However, our studies demonstrated that the infection-induced LSK cells exhibited poor engraftment, indicating that the LSK CD34− CD135− cell population contained few LT-HSCs." (PMID 22194881, 2011). "Interestingly, TfR1 expression was significantly higher in JUNV-infected CD34+ cells compared to UV-irradiated JUNV-infected cells, suggesting that JUNV infection promotes further infection." (PMID 20419155, 2010). "When the AC133 marker was used to purify the most primitive CD34+ cells from cord blood, infection with HIV-1 was not possible." (PMID 19112504, 2008). "While the mock and the eGFP sorted CD34+ cells transduced with the parental MND/EGFP vector were highly permissive to viral replication, cells expressing the MND/eGFP U16RBE resulted in over 4 logs of inhibition out to 28 days post infection." (PMID 16712721, 2006). "However, following latent infection of CD34+ pluripotent stem cells (HPCs), pp71 is retained in the cytoplasm and thus fails to disrupt PML-NB-induced defenses, suggesting cell type and/or infection stage specificity." (PMID 41373712, 2025). "HIV-1-infected CD34-NSG mice (n = 14) underwent CEST MRI to quantify metabolic profiles in the cortex, hippocampus, hypothalamus, piriform cortex, and thalamus at three timepoints: pre-infection (Week 0), 6 weeks-post-infection (WPI), and after 6 weeks of ART- or vehicle-treatment (12 WPI)." (PMID 40630517, 2025).
infection (continued). "This narrow tropism contrasts with that of the MVMp, whose toxic infection capacity for the CD34+ human primitive precursors results in the absence of clonogenic activity of precursors committed to both the erythroid (BFU-E to the CFU-E) and the myeloid (CFU-GM) lineages." (PMID 41143413, 2025). "CD34+ HPCs were engrafted into NSG mice to reconstitute components of the human immune system (from here on referred to as human immune system (HIS) mice), while CD19+ B cells were transformed into lymphoblastoid cell lines (LCL) by infection with the oncogenic Epstein–Barr virus (EBV)." (PMID 38986249, 2024). "In addition, the activation of TLR2 and TLR4 in CD34+ cells and megakaryocytes in the presence of TPO may warrant platelet provision during infection episodes by an autocrine IL-6 loop triggered by the PI3K/NF-κB axes." (PMID 36674552, 2023). "In addition to direct infection of the BCSFB, this route of infection may also occur via infected leukocytes, particularly CD34+ hematopoietic progenitor cells." (PMID 37896889, 2023). "However, the virus does not appear to replicate well within B cells or CD34+ cells in vitro; the virus bound to B cells mostly remains at the cell surface and JCPyV in primary B cells or B cell lines results in an infection rate under 5%." (PMID 37896889, 2023). "Infection with an HCMV mutant lacking miR-US25-1 resulted in increased proliferation of CD34+ HPCs but decreased the proportion of genome-containing cells in latency culture, indicating that miR-US25-1 contribute to viral genome maintenance by preventing excessive cell proliferation." (PMID 35746686, 2022). "As early as 2007, a clinical study demonstrated that all patients who underwent co-transplantation of ex vivo expanded MSC with HLA-disparate CD34+ cells showed continuous hematopoietic engraftment, without additional infection compared to in the control group." (PMID 35720412, 2022). "In addition to promoting lytic infections in many cell types including fibroblasts and smooth muscle cells, HCMV also establishes latent infections in undifferentiated myeloid lineage cells, such as monocytes and CD34+ hematopoietic progenitor cells." (PMID 35083168, 2021). "Moreover, infection with an HCMV mutant lacking miR-US25-1 resulted in increased proliferation of CD34+ HPCs and a decrease in the proportion of genome-containing cells at the end of latency culture." (PMID 33824207, 2021). "The hypothesis that miR-US5-2-mediated Gab1 down-regulation has a critical role in switching off the HCMV latency program in favor of a lytic infection is also supported by data showing that pharmacological MAPK and PI3K inhibitors enhance HCMV reactivation in CD34+ hematopoietic progenitor cells." (PMID 35083168, 2021). "This could explain why proliferation is not fully restored to mock levels during infection of CD34+ HPCs with ΔmiR-US25-1." (PMID 33824207, 2021). "The targeting of MRP1 by UL138 increases susceptibility of CD34+ and CD14+ cells to vincristine, and while this provides a possible method to target infected cells, it is not clear how the regulation of MRP-1 impacts infection." (PMID 32630219, 2020). "We transduced rhesus CD34+ cells with the optimized reverse-oriented vector and forward-oriented vector including a GFP or enhanced yellow fluorescent protein (YFP) gene at a multiplicity of infection (MOI) 50 in a competitive repopulation assay following 10 Gy total body irradiation." (PMID 31578323, 2019). "Some previous studies have shown that primary CD34+ myeloid progenitor cells do not express lytic viral genes upon infection but rather that viral genomes in these cells are inactivated upon entry and remain quiescent until they receive signals that induce them to differentiate." (PMID 30206173, 2018).
infection (continued). "Infection of the cells with the pLVX-mCherry vector did not affect the efficiency of the shRNA, as we observed a similar reduction in Elmo1 mRNA compared to CD34+ cells isolated from SH02 tumors that did not express the mCherry (50% reduction for construct #1 and 60% reduction for construct #2." (PMID 28219480, 2017). "Our modelling also did not include ×4 infection of CD34+ HSC." (PMID 24945407, 2014). "Besides the direct infection of specific targets, HIV employs several pathogenetic mechanisms among which apoptosis activation plays a pivotal role in several cell models such as CD34+ hematopoietic progenitor cells and T cells." (PMID 21612582, 2011). "The engraftment and infection procedures employed by these studies resulted in an infection lasting only 43 days, after which the animals died; however, when the CD34+ cells were transplanted without myeloablation methods, the mice were able to survive for longer than 300 days." (PMID 19674458, 2009). "In addition, we and others have previously shown that HCMV can infect CD34+ progenitor cells in the bone marrow, but this infection was not productive." (PMID 18941519, 2008). "In fact, CD34+ HPCs have been shown to secrete the CCR5 ligands MIP-1α, MIP-1β, and RANTES, and the CXCR4 ligand SDF-1, which may compete with infectious HIV-1, either CCR5- or CXCR4-utilizing virus, and consequently block infection." (PMID 19112504, 2008). "Finally, infection of CD34+ HPCs with wild type HCMV and a mutant lacking miR-US25-1 showed that miR-US25-1 increases the retention of latent viral genomes because cells infected with the mutant virus contained fewer genomes relative to those infected with wild type virus." (PMID 34299120, 2021). "Thus, several TFBSs lost upon NCCR rearrangement might control the promoter activity of archetype JCV in CD34+ cells during latent or persistent infection and are not required for lytic infection of prototype JCV in the brain." (PMID 34835120, 2021). "Collectively, this evidence suggests that unknown activities of live pathogen infection regulate myeloid differentiation involving an IL-6R-mediated process and implies cross-talking of regulatory pathways between live Mtb, IL-6 and IFN signaling to boost myeloid differentiation of CD34+ cells." (PMID 31637998, 2019). "After 14 days of infection, UCB replicates 1–3 did not produce infectious virus particles in the sorted cells of CD133+ and CD34+." (PMID 37386042, 2023). "MSCs used in here retained after infection hematopoietic stem cell markers (lack of CD45, CD34, CD11b, CD19, and HLA-DR and presence of CD105, CD73 and CD90)." (PMID 32775618, 2020). "A previous report tested coculture of CD34+ and fetal thymic epithelial cells in the presence or absence of HIV-1, observing that infection led to the inhibition of thymocyte maturation at early stages (CD44+CD25−CD3−)." (PMID 30761146, 2019). "Undifferentiated hematopoietic cells, such as CD34+ human progenitor cells (HPCs) and CD14+ monocytes, do not support a replicative infection and serve as a reservoir for HCMV latency as well as a platform for viral dissemination throughout the host." (PMID 30127257, 2018). "The survival effect we observe in neutrophils, involving a likely virion–cell surface interaction, is similar to that observed during non-permissive infection of CD14+ and CD34+ cells, where ERK and PI3K signaling were shown to be key." (PMID 28993776, 2017). "However, following latent infection of CD34+ HPCs, pp71 is retained in the cytoplasm and thus fails to disrupt PML-NB-driven defenses, which suggests cell type and/or infection phase specificity." (PMID 37439556, 2023). "Infection of THP-1 cells with a mutant virus lacking iP1 and/or iP2 failed to accumulate IE proteins and undergo reactivation, and CD34+ HPCs infected with mutant virus similarly displayed defects in reactivation, indicating that iP1 and iP2 are required for efficient reactivation of HCMV." (PMID 34299120, 2021).